DDR2 (discoidin domain receptor tyrosine kinase 2)
Diseases named in the same sentence as DDR2 in open-access papers (continued):
Sharing a sentence is not in itself a finding about the gene and the disease.
tumor (continued). "In the presence of Ddr2+/+ CAFs, there was increased lung colonization compared to that in animals injected with tumor cells alone." (PMID 34477203, 2021). "On the other hand, little is known about the role of DDR2 in the acquisition of tumor cell resistance to chemotherapy." (PMID 34174931, 2021). "In stromal Cancer-Associated Fibroblasts (CAFs), DDR2 promotes ECM and collagen fibrous tissue deposition, and enhances tumor cell invasion and metastasis." (PMID 34805157, 2021). "In many cancers, DDR1 or DDR2 are overexpressed, suggesting a role for DDRs in tumor development and metastasis." (PMID 33917302, 2021). "Accordingly, inhibition of DDR2 expression decreases collagen deposition and fiber alignment and thereby tumor growth, migration and invasion are reduced." (PMID 33917302, 2021). "Compound 44 also inhibited DDR2 phosphorylation and suppressed tumor growth with tumor growth inhibition rates (TGI) of 82.8% in mice bearing NCI-H2286 (DDR-dependent cell line) at doses of 10 mg/kg for 10 consecutive days." (PMID 34207360, 2021). "It is known that DDR2 can be involved in tumor progression through the tumor neo-angiogenesis process." (PMID 35004699, 2021). "We found that +DDR1b/+COL1 and +DDR2/+COL1 tumours displayed a 1.62- and 3.23-fold increase in CTGF mRNA levels, respectively, when compared to −DDR1b or −DDR2 tumours in COL1." (PMID 32047176, 2020). "In contrast, +DDR2 tumours displayed higher levels of total YAP1 when compared to -DDR2 tumours (p = 0.057)." (PMID 32047176, 2020). "We have previously observed that these cell lines are able to metastasize the liver, were tumor development is collagen-dependent by a mechanism partially dependent on DDR2, the other member of the DDR family." (PMID 32090682, 2020). "Using an inducible expression system in human HT1080 fibrosarcoma cells, we investigated the role of DDR1b and DDR2 on primary tumour growth and experimental lung metastases." (PMID 32047176, 2020). "DDR1 and DDR2 play an important role in the tumor microenvironment which is involved in the dissemination of tumor cells." (PMID 32984031, 2020). "Discoidin domain receptor tyrosine kinase 2 (DDR2) is an RTK related to a tumor growth promoting effect, similar to that described for the other ceRNAS." (PMID 32605009, 2020). "More recently, several ATP-site inhibitors have been developed to specifically inhibit DDR1 and/or DDR2 activity, and they display significant anti-tumor activities in several cancer models, including CRC cells." (PMID 32117772, 2020). "The small molecule inhibitor WRG-28 targets DDR2, thereby inhibiting tumor–stromal interactions as well as tumor invasion and migration." (PMID 33006013, 2020). "Dasatinib, nilotinib, a DDR1 blocking antibody, the selective DDR1 inhibitors 7rh and DDR1-IN-1 and the selective allosteric DDR2 inhibitor WRG-28 were shown to efficiently prevent DDR-mediated tumor progression in preclinical models." (PMID 32793493, 2020). "In other cancers, fibrillar collagen and its receptor, DDR2, work in concert to promote a pro-tumorigenic environment via both the tumor microenvironment and tumor cells." (PMID 31061140, 2019). "DDR1 is found preferentially expressed in highly invasive epithelial tumor cells, whereas DDR2 is expressed in tumor stroma." (PMID 31116512, 2019). "Herein we show that in the absence of full Talin1 activation in response to collagen activated DDR2 there are clear functional sequelae in mesenchymal cells in culture and in tumor progression in vivo." (PMID 31144616, 2019). "In contrast, in Ddr2-/- FSP1cre tumor organoids there was significantly decreased active β1 Integrin level in CAFs, while still present and unchanged in tumor cells that are Ddr2+/+ in these mice (quantified in D and E)." (PMID 31144616, 2019).
tumor (continued). "Previous studies have shown that CD45+DDR2+ cells differentiate into activated fibroblasts and immune cells in inflammatory tissue environments (i.e., tumor, inflammatory lung)." (PMID 31015794, 2019). "In ubiquitous Ddr2-/- tumor organoids (all cells Ddr2-/-) active β1 Integrin level was decreased in both CAFs and tumor cells (quantified in D and E)." (PMID 31144616, 2019). "The action of DDR2 in tumor CAFs is thus critical for remodeling collagen fibers at the tumor-stromal boundary to generate a physically permissive tumor microenvironment for tumor cell invasion and metastases." (PMID 31144616, 2019). "(C) Number of total lung metastases in MMTV-PyMT (WT) (n = 18 mice) or FSP1cre; Ddr2fl/fl; MMTV-PyMT (Ddr2-/-; FSP1cre) (n = 10 mice) mice at termination (@20 weeks or when a single tumor reached 2 cm)." (PMID 31144616, 2019). "Previous studies in our lab have shown that CD45+DDR2+ cells are a circulating progenitor population that home to normal tissue as well as pathological environments, including inflammatory tissue and tumor microenvironments." (PMID 31015794, 2019). "As a result, the overall tumor matrix organization controlled by DDR2 signaling in tumors, and CAFs specifically, likely involves both its regulation of collagen binding β1 Integrin and SNAIL1." (PMID 31144616, 2019). "Consistent with the change in overall tumor stromal stiffness, pMLC staining of tumor slices revealed significantly less overall pMLC activity in Ddr2-/- FSP1cre tumors." (PMID 31144616, 2019). "Similar results were observed for AML4-ALK, BRAF and DDR2 mutant or MYC amplified tumours in The Cancer Genome Atlas (TCGA) data set." (PMID 28220783, 2017). "Only one previous study has reported the identification of DDR2 amplification as a novel therapeutic target by whole genome sequencing analysis of a single WDLPS tumor." (PMID 28099935, 2017). "DDR2 is well known to be activated by fibrillar type I collagen and this property is crucial in the down-regulation of tumor cell proliferation by this receptor." (PMID 27121132, 2016). "At 28 days post-orthotopic transplantation, we found that DDR2 knockdown reduced the number of disseminated metastases and tumor weights in the gastric walls." (PMID 26934957, 2016). "Strikingly, DDR2 expression was evidently correlated with tumor number, vascular invasion, Edmondson-Steiner grade and TNM stage." (PMID 26362312, 2015). "Several studies have found that DDR2 is up-regulated in many tumor types and facilitates tumor progression." (PMID 26362312, 2015). "In this study, we found that DDR2 was more highly expressed in HCC tissues than that in non-tumor tissues, and DDR2 overexpression was correlated with poor clinicopathological features and outcome of HCC patients." (PMID 26362312, 2015). "The univariate analysis revealed that DDR2 level, HBsAg status, tumor number, vascular invasion, Edmondson-Steiner grade and TNM stage were the prognosis factors for HCC patients." (PMID 26362312, 2015). "Our data indicate that DDR2 expression is associated with EMT phenotype and tumor cell migration and invasion in HCC (P < 0.01, respectively)." (PMID 26362312, 2015). "Our findings also showed that DDR2 expression was significantly higher in HCC tissues compared with matched normal tumor-adjacent tissues." (PMID 26362312, 2015). "Compared to the control treatment, DDR2-S131C overexpression treatment dramatically increased tumor growth, which was demonstrated by significantly increased tumor size and weight." (PMID 24885564, 2014). "Large-scale phosphoproteomic screens of human tumours have identified DDR2 to be highly phosphorylated in a subset of non-small-cell lung cancers, cholangiocarcinomas and sarcomas." (PMID 23822953, 2013). "The contrasting oncogenic and tumour-suppressive properties of DDR2 are likely to be context-dependent." (PMID 23822953, 2013).
tumor (continued). "Consistent with the tumour-suppressive role of DDR2 in cancer cells induced by fibrillar collagen, we found that wild-type DDR2 expression greatly reduced colony formation compared with the control cells." (PMID 23822953, 2013). "Of note, DDR1 appears to be preferentially expressed in tumour cells, whereas DDR2 is expressed in tumour stroma." (PMID 17299390, 2007). "Discoidin domain receptor 1 was shown to be upregulated in tumour vs normal tissue, whereas DDR2 was downregulated." (PMID 17299390, 2007). "Discoidin domain receptor 1 was shown to be upregulated by 2.15-fold (P=0.0005), and DDR2 downregulated by an equivalent amount (1.94-fold, P=0.0001) in tumour tissue compared with matched normal samples." (PMID 17299390, 2007). "An additional 23 matched tumour and normal tissues were tested for differential expression of DDR1 and DDR2, and previously reported somatic mutations." (PMID 17299390, 2007). "Discoidin domain receptor 1 was found to be significantly upregulated by 2.15-fold (P=0.0005) and DDR2 significantly downregulated to an equivalent extent (P=0.0001) in tumour vs normal lung tissue." (PMID 17299390, 2007). "Mesenchymal markers such as CDH2 (log2fc = 0.57) and DDR2 (log2fc = 0.63) are elevated in poor-prognosis tumours, suggesting that upregulation of mesenchymal genes may contribute to more aggressive tumour phenotypes." (PMID 41007296, 2025). "Additionally, DDR2 drives collagen production by CAFs through the upregulation of arginase-1 transcription, further enhancing tumor invasiveness." (PMID 40563472, 2025). "CAFs with high DDR2 or arginase promote tumor colonization in the omentum." (PMID 37996700, 2024). "CAFs from WT and Ddr2−/− tumor-bearing mice were isolated as previously published." (PMID 37996700, 2024). "Given our findings on the importance of CAF DDR2, it is possible that fibroblast DDR2 may also contribute to anti-tumor immunity." (PMID 37996700, 2024). "Similarly, the addition of exogenous polyamines to CM from DDR2-depleted CAFs led to increased tumor cell invasion." (PMID 37996700, 2024). "Both polyamines rescued the tumor cell invasion defect of CM from Ddr2-depleted CAFs." (PMID 37996700, 2024). "A prior study showed that tumor cell DDR2 plays a role in response to anti-PD1 therapy." (PMID 37996700, 2024). "Moreover, the supplementation of exogenous polyamines to CM derived from DDR2-depleted CAFs increased tumor cell invasion." (PMID 38903506, 2024). "Indeed, studies have identified multiple effects of DDR1 and DDR2 on tumor growth and metastasis when expressed on tumor and CAFs." (PMID 37662958, 2023). "Meanwhile, DDR2 could be an effective target for enhancing tumor responses to anti-PD-1 according to recent research, which has proven that targeting DDR2 alongside PD-1 inhibitors exerts a more significant treatment effect among various cancers." (PMID 36992198, 2023). "Furthermore, the inhibition of DDR2 in conjunction with anti-PD-1 therapy has been observed to synergistically control tumor growth and metastasis in both cell line and mouse model studies." (PMID 38332915, 2023). "DDR2 inhibition in combination with PD-1 blockade has also demonstrated reduced tumor growth." (PMID 37662958, 2023). "Taken together, these results suggest that DDR2 may participate in tumor cells growth and permanence." (PMID 35711892, 2022). "Of particular interest was periostin (POSTN), which was found to have a significantly higher expression in DDR2-expressing NOFs co-cultured with ES2 tumor cells (NOF siCTRL + ES2) compared to DDR2-depleted NOFs co-cultured with tumor cells (NOF siDDR2 + ES2) (Fold change = 2.0, p = 0.03)." (PMID 35884543, 2022). "To determine if DDR2′s regulation of periostin in CAFs has an effect on tumor cell implantation in vivo, we injected ES2 cells and patient-derived CAFs into NCr nude mice and monitored ability to implant and form metastatic nodules in an intraperitoneal xenograft model." (PMID 35884543, 2022).
tumor (continued). "We aimed to define the role of DDR2′s modulation of POSTN in CAFs on tumor cell clearance of HPMCs." (PMID 35884543, 2022). "The collagen-binding RTK DDR2 is known to play important roles in tumor progression." (PMID 35711892, 2022). "We aimed to study the effect of DDR2′s modulation of POSTN in CAFs on tumor cell attachment." (PMID 35884543, 2022). "The role of DDR2 in BC development has been uncovered recently, with special emphasis on its ability to stimulate the secretion of collagen-dependent proteases by tumor cells in postpartum-related carcinomas, activating their migratory and invasive potentials, as well as triggering metastasis." (PMID 35711892, 2022). "However, overexpression of POSTN in DDR2-depleted CAFs led to an increase in tumor spreading as measured by sprout area ratio." (PMID 35884543, 2022). "Given we identified that DDR2 expression in CAFs can further promote metastasis through regulation of tumor spheroid branching, we asked whether there were particular secreted proteins that contributed to fibroblast regulation of metastasis." (PMID 35884543, 2022). "Although CAFs and TAMs communication with tumor cells is essential for BC progression, the role of DDR2 during this interaction remains unclear." (PMID 35711892, 2022). "Rather, the actions of DDR2 in tumor cells predominantly affect tumor cell motility and invasion." (PMID 34477203, 2021). "The group 1 TK DDR2 has been implicated recently in immune evasion by BCa tumors, whereas targeting PTK7 (also a group 1 TK) has been reported to induce regression of several tumor model systems." (PMID 34292953, 2021). "Re-expression of WT DDR2 in DDR2-depleted tumor cells completely rescued this activity." (PMID 34477203, 2021). "In another approach to confirm that DDR2 activity in CAFs is important for paracrine regulation of tumor cell invasion through Matrigel, we utilized a small-molecule allosteric inhibitor of DDR2 that interacts with the extracellular domain of DDR2 (CR13452 Rottapharm Biotech S.r.l., Monza, Italy)." (PMID 34477203, 2021). "All cells were embedded in 3D collagen I. Ddr2+/+ and WT-rescued Ddr2−/− CAFs enhanced both the average velocity of collective migration and directed collective migration (migration efficiency towards the upper channel containing CAFs) of tumor organoids." (PMID 34477203, 2021). "Thus, endothelial cells are also able to form linear invadosomes and to contribute to the formation of new vessels, and consequently to tumor progression by a process which is dependent on DDR2." (PMID 35004699, 2021). "To determine whether the action of DDR2 in tumor cells was required for these paracrine actions, we generated conditioned medium from tumor cells expressing various DDR2 receptor mutants." (PMID 34477203, 2021). "DDR2 action in CAFs can also increase tumor cell invasiveness through paracrine regulation." (PMID 34477203, 2021). "In contrast, tumor cells encounter fibrillar collagens only after invasion through the basement membrane; therefore, tyrosine kinase-independent effects of DDR2 may be more relevant in tumor cells." (PMID 34477203, 2021). "The conditioned medium was concentrated through a 10 kDa filter to remove peptide fragments, and then Matrigel plugs were pretreated with equivalent amounts of conditioned medium prior to the addition of parental tumor cells (i.e. cells expressing endogenous WT DDR2)." (PMID 34477203, 2021). "More and more articles report the involvement of DDR1 and/or DDR2 in cancer and tumor invasion." (PMID 35004699, 2021). "We set out to determine whether DDR2 exhibited tyrosine kinase-independent actions in tumor cells and tumor stromal cells, and if so, what the impact on tumor cell biology in ex vivo culture systems and in vivo would be." (PMID 34477203, 2021). "How exactly and in which circumstances DDR1 and DDR2 may regulate human tumor evasion, particularly in CRC, deserve further investigation." (PMID 32117772, 2020).
tumor (continued). "Interestingly, EMT was reported to rely on the switch from DDR1 (epithelial) to DDR2 (mesenchymal) expression, although various reports implicate both DDR1 and DDR2 in EMT-mediated tumor cell invasion." (PMID 32793493, 2020). "Of note, although our data showed differences between DDR1b- and DDR2-expressing tumours in YAP1 regulation and other signalling molecules, these may not necessarily reflect differences between DDRs." (PMID 32047176, 2020). "DDR2 upregulation in the stroma also may participate in this malignant process by promoting tumor stiffness through integrin-mediated mechanotransduction in CAFs and by promoting stromal-breast cancer cell interaction for metastatic colonization." (PMID 32117772, 2020). "Finally, an in vivo functional genomic study using isogenic mouse cancer models to identify genes the inhibition of which potentiates the response to anti-PD1 immunotherapy showed that tumor DDR2 is an essential regulator of MSI+ CRC cell immune evasion." (PMID 32117772, 2020). "Both DDR1 and DDR2 were shown to promote tumor cell proliferation, survival, and migration." (PMID 32793493, 2020). "However, phosphorylation of AKT (at S473) was significantly higher only in +DDR2/+COL1 tumours, consistent with the role of AKT in supporting cell proliferation in cancer." (PMID 32047176, 2020). "Similarly, targeting DDR2 activity with dasatinib enhanced the tumor response to anti-PD1 immunotherapy in a CRC mouse model." (PMID 32117772, 2020). "DDR2 in tumor cells is also involved in the invasion process." (PMID 33006013, 2020). "DDR1 and DDR2 have been demonstrated to predominantly regulate tumor progression." (PMID 31130862, 2019). "For example, in 3D collagen matrix, DDR2 is able to suppress tumor cell growth." (PMID 31130862, 2019). "Altogether, these data suggest that biological collagen aging could increase tumor cell proliferation by reducingthe activation of the key matrix sensor DDR2." (PMID 27121132, 2016). "Furthermore, high DDR2 level was evidently correlated with tumor number, vascular invasion, Edmondson-Steiner grade and TNM stage in HCC." (PMID 26362312, 2015). "Taken together, our results demonstrated that DDR2 overexpression may promote tumor progression and is a critical factor for prognosis determination in HCC patients." (PMID 26362312, 2015). "The lung is an important site of collagen deposition and modification (such as by cross-linking) during tumour progression and the tumour-suppressive properties of DDR2 may be more pertinent in this context." (PMID 23822953, 2013). "Ongoing studies on the interaction of LOX and DDR2 signaling in the tumor microenvironment may further explain the relationship between collagen dysregulation and cancer invasion and metastasis." (PMID 21288331, 2011). "However, the role of DDR2 in tumor differentiation remains unclear, necessitating further investigation." (PMID 40563472, 2025). "Furthermore, expression of NF2, another tumor suppressor, was increased after DDR2 RNAi." (PMID 38538106, 2024). "Interestingly, the expression of DDR2 in D0 tumor samples was the highest, indicating that early drug treatment may be more effective in slowing down the tumor growth." (PMID 38554776, 2024). "On the other hand, DDR2 might act as a liver metastasis suppressor through tumour-activated HSCs." (PMID 37007062, 2023). "This could be controlled by the wide spectrum of DDR2 mediated changes in the tumor stroma." (PMID 35711892, 2022). "We next asked whether the action of DDR2 in OmCAFs can contribute to tumor metastasis." (PMID 35884543, 2022). "In addition, overexpressing POSTN in DDR2-depleted CAFs led to an increase in tumor cell invasion." (PMID 35884543, 2022). "Thus, we asked whether DDR2 signaling in CAFs also affected paracrine regulation of tumor cell invasion and migration." (PMID 34477203, 2021). "In addition, DDR2 expression in tumor cells and in the metastatic niche may influence tumor metastatic colonization." (PMID 33917302, 2021).